SEMA4C (semaphorin 4C)
Diseases named in the same sentence as SEMA4C in open-access papers (continued):
Sharing a sentence is not in itself a finding about the gene and the disease.
cutaneous melanoma (1 paper, 2014). A primary melanoma arising from atypical melanocytes in the skin. "To date, there is no published evidence of the direct involvement of SEMA4C in cancer, but somatic point mutations in SEMA4C were also reported by TCGA in 4% of the cutaneous melanomas." (PMID 25193853, 2014).
fibrosis (1 paper, 2025). the formation of excess fibrous connective tissue in an organ or tissue in a reparative or reactive process. "Increased expression of circNlgn led to compromised cardiac function and enhanced cardiac fibrosis by upregulating growth arrest and DNA damage inducible protein 45 b (Gadd45b), semaphorin-4C (Sema4C), and RAD50 and activating p38 and p-JNK via its translated Nlgn173 in transgenic hearts." (PMID 40563440, 2025).
glioma (1 paper, 2015). A benign or malignant brain and spinal cord tumor that arises from glial cells (astrocytes, oligodendrocytes, ependymal cells). "SEMA4C-Fc stimulation of LN229 glioma cells led to a 3-fold increase in the invasive migration relative to control." (PMID 25762646, 2015). "Upon stimulation by Sema4C, Plexin-B2 signaling: i) alters actin cytoskeleton and cell morphology, ii) enhances glioma cell migration, and iii) promotes glioma invasive growth, in particular, along microvasculature." (PMID 25762646, 2015). "Notwithstanding, in both LN229 and U87MG glioma cells, Sema4C/Plexin-B2 signaling promotes cell migration in vitro, synergistic Met activation, and vascularization of tumor mass, thus underscoring generality of Plexin-B2 function for glioma progression." (PMID 25762646, 2015). "The reduction in actin stress fibers and the increased formation of membrane ruffles by SEMA4C-Fc stimulation were strongly attenuated in Plexin-B2 shRNA knockdown lines, indicating that the Sema4C-triggered actin dynamics in glioma cells are mediated through Plexin-B2." (PMID 25762646, 2015). "It is therefore likely that endothelial/glioma cell interactions might be mediated through Sema4C/Plexin-B2 signal transduction." (PMID 25762646, 2015). "In addition, reverse signaling of Sema4s has been reported, it is thus conceivable that Plexin-B2 expressed by glioma cells may signal through Sema4C on endothelial cells to promote vascular proliferation." (PMID 25762646, 2015).
lymph node metastasis (1 paper, 2020). "Furthermore, high SEMA4C expression positively correlated with lymph node metastasis, distant metastasis, and poor overall survival of CRC patients." (PMID 33177246, 2020).
myopia (1 paper, 2019). "Our study identified methylation differences in the semaphorins, such as SEMA3F, SEMA4B, SEMA4C and SEMA5A that were significantly associated with myopia." (PMID 30858441, 2019).
tumor (23 papers, 2015 to 2025). "For instance, Sema3A, Sema4C, and Sema4D promote tumor progression by attracting tumor-associated macrophages." (PMID 40103807, 2025). "Except in the nervous system, studies demonstrated that sema4c was implicated in other biological processes, including cell migration, tumor development, terminal myogenic differentiation and EMT." (PMID 36010604, 2022). "For instance, Sema3A, Sema4C, and Sema4D have been found to promote tumor progression by enrichment of tumor-associated macrophages in TME." (PMID 35155237, 2022). "Tumor-associated LECs actively participate in lymphatic metastasis by highly expressing soluble semaphorin 4C (sSEMA4C), which promotes lymphangiogenesis by activating PlexinB2-ERBB2 signaling in LECs and facilitates tumor proliferation and migration by activating PlexinB2-MET signaling." (PMID 37234990, 2023). "Furthermore, studies have demonstrated that sema4C was also implicated in biological events outside the nervous system, such as cell migration, tumor development, and terminal myogenic differentiation." (PMID 36010604, 2022). "SEMA4C mRNA expression was significantly associated with the histological tumor type (P = 0.019), pathologic stage (P = 0.008), lymph node metastasis (P = 0.011), distant metastasis (P = 0.013), microsatellite instability (MSI) status (P = 0.038) and CMS subtypes (P = 2.091E-9)." (PMID 33177246, 2020). "According to this model, the inhibition of angiogenesis observed in Plexin-B2-depleted GBM xenografts in mice may be due to reduced tumor cell perivascular spread associated with the disruption of the Sema4C/Plexin-B2-mediated pro-migratory pathway." (PMID 31052281, 2019). "SEMA4C KD alone mimicked PB2 KO in reducing the average size and numbers of WT tumor cell clusters, whereas loss of both PLXNB2 and SEMA4C together did not have an additional impact on cluster size compared to PB2 KO alone." (PMID 40818975, 2025). "Interactions of PLXNB2 with its ligands SEMA4C on tumor cells and SEMA4A on myeloid cells (monocytes) promote homotypic and heterotypic CTC cluster formation, respectively, thereby driving lung metastasis." (PMID 40818975, 2025). "SEMA4C, a semaphorin, can promote tumor development and serve as a candidate treatment target for cancers." (PMID 39950044, 2025). "For example, SEMA4C promotes tumor growth by serving as an attractant recruiter of tumor associated macrophages (TAMs)." (PMID 35676688, 2022). "In fact, targeting Sema4C/PlexinB2 signaling resulted in cell cycle arrest in G2/M phase, upregulation of tumor-suppressor genes and cell senescence." (PMID 33537086, 2021). "Overall, these results demonstrate that SEMA4C mRNA levels are significantly altered in the tumor tissues compared to the corresponding normal tissues." (PMID 33177246, 2020). "Semaphorin 4C (SEMA4C), is an important regulator of axonal guidance and aggravates tumor development." (PMID 33177246, 2020). "High expression of SEMA4C was correlated with the proliferation of tumor cells and the aggregation of macrophages in BC." (PMID 32296631, 2020). "PR cells were sensitized by enforced expression of miR-125b or Sema4C depletion, while miR-25-3p overexpression sensitized CR cells to cisplatin in HeLa CR cells and suppressed tumor growth in mice." (PMID 31776419, 2019). "Upon stimulation with recombinant human SEMA4C-Fc, tumor cells displayed a marked reduction in actin stress fibers and focal adhesions, and assumed a more rounded morphology with membrane ruffles formation at cell edges." (PMID 25762646, 2015). "Furthermore, in vitro assay also showed that the four risk genes (HSPA1A, SEMA4C, CDKN2A, ARHGAP4) were overexpressed in the tumor cells." (PMID 39950044, 2025). "PLXNB2 is identified as a driver that promotes both homotypic and heterotypic CTC clustering through its interactions with Semaphorin ligands SEMA4C on tumor cells and SEMA4A on monocytes, in addition to PLXNB2 functions in proliferation and other known functions." (PMID 40818975, 2025).
tumor (continued). "We hypothesized that SEMA4C is a primary ligand of PLXNB2 in driving homotypic tumor cell clusters in metastasis." (PMID 40818975, 2025). "In a further study, similarly, SEMA4C knockdown in MDA-MB-231 cells reduced tumour volumes and instances of lung and liver metastasis and also decreased macrophage infiltration, suggesting that SEMA4C may modulate immune recognition." (PMID 37685898, 2023). "Furthermore, miR-31-3p overexpression inhibited Sema4C-induced EMT to influence tumor cell migration and increase chemo-sensitivity to CDD." (PMID 31776419, 2019). "Furthermore, compared with the control group, enforced miR-31-3p expression notably inhibited the invasion and migration of tumor cells, suppressed Sema4C and Snail expression, and increased E-cadherin expression in Caski-CR cells." (PMID 31776419, 2019). "LINC00152 promotes the proliferation and tumor growth of HCC cells by sponging miR-125b and upregulating the expression of semaphorin-4C (SEMA4C)." (PMID 36033524, 2022). "IHC scores of Plexin-B2, SEMA4C, SEMA4D, and SEMA4 were calculated based on the percentage of stain present and the stain intensity of tumor cells in the tumor tissues of human patients and mouse models." (PMID 35570846, 2022). "On the other hand, SLC6A6 and SLC22A4 are transporters, SART3 is a tumor rejection antigen, VPS41 is involved in organelle development, SEMA4C is involved in axon guidance, and SHMT1 is an enzyme with involvement in glycine, serine, and threonine metabolism." (PMID 30973896, 2019). "SEMA4C is related to the proliferation, metastasis and invasion of a variety of tumor cells, but there is no relevant research on its influence mechanism on BC cells." (PMID 34747314, 2021). "Furthermore, CRC patients with high SEMA4C protein expression in the TMA-CRC cohort also showed poorer OS (P = 0.014) and tumor-free survival (TFS; P = 0.024) compared to those with low SEMA4C expression." (PMID 33177246, 2020). "To demonstrate the tumor-promoting role of SEMA4C in CRC, we developed knockdown vectors for SEMAC4 (si-SEMA4C#1, si-SEMA4C#2) alongside RNAi negative control vectors (si-NC) and transfected them into HT29 and SW480 cell lines." (PMID 40103807, 2025).
cancer (18 papers, 2014 to 2025). A tumor composed of atypical neoplastic, often pleomorphic cells that invade other tissues. "Wnt3a and Sema4C mediate mechanical hyperalgesia in contexts of cancer-associated or inflammatory pain respectively." (PMID 36231105, 2022). "Overexpression of Plexin-B2 and SEMA4C has been implicated in the poor prognosis in the cancers of bone, breast, and brain." (PMID 35570846, 2022). "In view of the role of miR-138 in cancer cells, we predicted the target of miR-138 and its targeting to SEMA4C by bioinformatics software and luciferase experiment." (PMID 34747314, 2021). "In summary, we discovered that Sema4C is more frequently upregulated, while miR-31-3p expression was obviously decreased in CC tissues and cancer cell lines." (PMID 31776419, 2019). "Semaphorin 4C (SEMA4C) is highly expressed in breast, lung, cervical and liver cancers." (PMID 33177246, 2020). "Overexpression of hsa-miR-134-5p in cancer cells exerts regulatory effects on BDNF and SEMA4C, thereby promoting the proliferation and invasion of SW1990 cells while inhibiting apoptosis." (PMID 38579169, 2024). "Sema4C, Sema4D, and Sema7A can be considered as promising biomarkers of TAM infiltration and can be used as prognostic indicators of cancer." (PMID 35155237, 2022). "Sema4C, the target of many miRNAs, is involved in EMT-mediated chemotherapeutic resistance of many malignant tumors." (PMID 31776419, 2019). "Among them, SEMA3F, SEMA4C, PLXNB1 and PLXNB2, involved in cancer progression and in immune system suppression, were highly expressed." (PMID 26784191, 2016).
infection (1 paper, 2016). The state of being infected such as from the introduction of a foreign agent such as serum, vaccine, antigenic substance or organism. "Viable Sema4C−/− mice did not have any overt phenotypic abnormalities, and did not display spontaneous increased susceptibility to infection." (PMID 28003812, 2016).
SEMA4C also shares sentences with these, for which no sentence is quoted: lung cancer (3 papers); rectal cancer (2); allergic disease (1); colorectal tumors (1); gastric cancer (1); lung (1); neurodegenerative disease (1); neuropathy (1); oral squamous cell carcinoma (1); osteosarcoma (1); ovarian carcinoma (1); prostate carcinoma (1); rectal adenocarcinoma (1); sarcoma (1); triple-negative breast carcinoma (1).